APOD (apolipoprotein D)
Diseases named in the same sentence as APOD in open-access papers (continued):
Sharing a sentence is not in itself a finding about the gene and the disease.
schizophrenia (13 papers, 2008 to 2023). A major psychotic disorder characterized by abnormalities in the perception or expression of reality. "Increased expression of APOD in the human prefrontal cortex during critical developmental periods is associated with increased susceptibility to schizophrenia." (PMID 24558408, 2014). "The association of a myelination-related module with schizophrenia is in line with a wide range of reported white matter abnormalities linked to the illness and genetic studies that have contributed a number of myelin and oligodendrocyte –related genes as candidate genes (e.g. APOD, PLP1, MAG)." (PMID 24070017, 2013). "Lipid-binding proteins ApoB, ApoD, ApoF, and ApoM were reduced in patients with schizophrenia, whereas ApoE was increased." (PMID 34741130, 2022). "In a study with humans, significantly elevated apoD levels have been observed in the amygdalae of subjects with schizophrenia." (PMID 34490028, 2021). "Initially this group compared apoD levels in six brain regions from healthy controls and Schizophrenia patients and discovered an approximate doubling of apoD levels in the dorsolateral prefrontal cortex of the Schizophrenia patients." (PMID 26829325, 2016). "However, ApoD is thought to play a role in the pathophysiology of schizophrenia." (PMID 24558408, 2014).
gastric cancer (12 papers, 2021 to 2025). A primary or metastatic malignant neoplasm involving the stomach. "We screened eight DDR-related genes (ZBTB7A, POLQ, CHEK1, NPDC1, RAMP1, AXIN2, SFRP2, and APOD) to establish a risk model, which can predict the prognosis of gastric cancer patients and guide the clinical implementation of immunotherapy." (PMID 36578802, 2022). "In gastric cancer, several bioinformatic analysis have revealed APOD as a component of gene-risk model and associated with tumor mutational burden and immune cell infiltration." (PMID 36389725, 2022). "APOD DNA/RNA methylation has been implicated in the pathogenesis of gastric cancer, and so studying APOD methylation in PE could provide valuable insights." (PMID 41366770, 2025). "In conclusion, APOD is the potentially high-risk gene with the highest mutation rate, and its high expression may promote the progression of gastric cancer." (PMID 36578802, 2022). "Elevated levels of APOD in gastric cancer (GC) have been shown to promote proliferation and metastasis via the Wnt/β-catenin/EMT axis." (PMID 40951343, 2025). "I with a logFC >1, we generated a gene signature of iGC stage progression (intestinal-type gastric cancer progression signature - iGCPS), composed of APOD, COL1A2, GEM, FSTL1, LUM and SPARC." (PMID 39563861, 2024). "These molecular characteristics were mainly driven by the eight NRGPI oncogenes (CYTL1, PLCL1, CNTN1, GRP, APOD, GPX3, FCN1, SERPINE1) as validated in the gastric cancer cell lines and clinical samples." (PMID 36389725, 2022). "APOD and SLC22A17 are dysregulated and can be used for prognosis in gastric cancer patients." (PMID 34306002, 2021).
atherosclerosis (10 papers, 2009 to 2025). A disease characterized by the build-up of fatty material and calcium deposition in the arterial wall resulting in partial or complete occlusion of the arterial lumen. "Increases in APOD expression were found to be correlated with altered lipid metabolism and the risk of atherosclerosis." (PMID 32635226, 2020). "We also report for the first time the down-regulation of ApoD in human atherosclerotic plaques, and although its association with atherosclerosis is indisputable its role is still not completely understood." (PMID 28128285, 2017). "Increased apoD depositionis detectable in atherosclerotic lesions of humans with establishedcardiovascular disease as well as mice with premature atherosclerosis.Moreover, apoD is associated with anti-oxidation and anti-stressactivities, contributing to lifespan expansion in fruit flies." (PMID 19946382, 2009). "Moreover, a significant reduction of APOD level had been reported in Tangier disease, which contributes the excessive accumulation of cholesterol in the body, and thereby increases the risk of developing atherosclerosis." (PMID 30813444, 2019). "Its reduced abundance in the current study mirrors observations from atherosclerosis models, where APOD has been shown to attenuate inflammatory responses and oxidative stress." (PMID 40981199, 2025). "Nonetheless,little is known about the role of apoD in lipoprotein metabolism and its impacton atherosclerosis." (PMID 19946382, 2009). "In atherosclerotic plaque tissue, downregulation of ApoD gene expression can be observed, which may indicate reduced protective effects by ApoD and unchecked CyPA-mediated proinflammatory effects in atherosclerosis." (PMID 29419744, 2018). "This has spurred us to conduct a comprehensivereview of apoD function in triglyceride and cholesterol metabolism to addressthe question of whether apoD is another significant player in the pathogenesisof atherosclerosis." (PMID 19946382, 2009). "Further studiesare warranted to distinguish whether apoD contributes to or protects againstthe development of atherosclerosis." (PMID 19946382, 2009). "Furthermore, a prior separate FHS investigation found that protein level of APOD is also decreased in MI new-onset patients compared to controls, providing orthogonal evidence for APOD as an attractive novel candidate for clinical and subclinical atherosclerosis." (PMID 33568140, 2021). "Notably, APOD, encoding a component of high-density lipoprotein, was expressed significantly lower in both early MI (FDR = 0.007) and in high CAC (FDR = 0.01) compared with controls, respectively, highlighting a novel candidate for both MI and subclinical atherosclerosis." (PMID 33568140, 2021). "In the context of a high fat-high cholesterol diet, apoD deficiency in female mice is associated with increases in both plasma HDL and LDL-cholesterol levels, reflecting changes in expression of SR-BI and LDL receptors, which may impact diet-induced atherosclerosis." (PMID 25548917, 2014). "However, it is not yet clear whether this increase in apoD in these conditions refers to its role in inducing atherosclerosis or whether it represents a compensatory adaptive mechanism to changes observed in cardiovascular disease." (PMID 32921312, 2020).
COVID-19 (10 papers, 2021 to 2023). A disease caused by infection with severe acute respiratory syndrome coronavirus 2. "Multiple proteomics studies have associated plasma ApoD levels with both COVID-19 severity and mortality." (PMID 37343697, 2023). "In our previous work, we identified galectin-3 binding protein (LGALS3BP), as well as ApoD, as interactors of the spike through immunoprecipitation-MS of plasma of patients with COVID-19 supplemented with recombinant spike protein." (PMID 37343697, 2023). "Our previous study using immunoprecipitation MS in plasma from COVID-19 patients, supported a potential interaction of ApoD with the SARS-CoV-2 spike protein." (PMID 37343697, 2023). "We also found abnormalities in apolipoprotein levels in COVID-19 survivors 6 months after discharge; specifically, apolipoprotein D (APOD) and apolipoprotein M (APOM) levels were demonstrated to be reduced." (PMID 35288537, 2022). "Also, according to IPA analysis, some of them have been associated with viral infection (APOD, APOH, SERPINA1), severe COVID-19 (APOD, APOH, PCYOX1), or leukocyte migration (APOD, IGHV3-13, IGHV3-23, SERPINA1, IGLC7, IGLV3-21)." (PMID 35397534, 2022). "In addition to ApoA-I, most of the apolipoproteins classically associated with HDLs were less abundant in COVID-19 HDL particles, including ApoA-II, ApoC-I, II, III, IV, ApoA-IV, ApoC-I, ApoJ, Apo(a), ApoE, ApoM, ApoD, ApoB100 and ApoF." (PMID 33504824, 2021). "The application of XL-MS on plasma from COVID-19 patients revealed acute-phase HDL remodeling, dominated by SAA that also interacts with ApoD." (PMID 37343697, 2023). "However, our results show that apolipoprotein D (APOD) and APOM levels were reduced in COVID-19 survivors 6 months after discharge." (PMID 35288537, 2022). "In particularwe observed a decrease in the HDL components APOA4 and APOC1 in both COVID-19 non-ICU and ICU/F patients (cluster 3) while APOA2, APOD, APOH, APOM and the HDL-associated PON1 protein appear to be decreased mainly in COVID-19 non-ICU patients (cluster 7)." (PMID 36348270, 2022). "Apart from apolipoprotein D (APOD), LGALS3BP was the only protein to be retrieved to a greater extent with spike glycoprotein from plasma of COVID-19 ICU patients compared to COVID-19-negative plasma." (PMID 34099652, 2021).
prostate carcinoma (9 papers, 2013 to 2023). A carcinoma that arises from epithelial cells of the prostate gland. "Another group also reported that APOD was highly expressed in prostate cancer and high grade prostatic intraepithelial neoplasia compared with adjacent normal tissue." (PMID 33492335, 2021). "Firstly, APOD (apolipoprotein D) is a lipocalin that participates in various cellular processes, including cytoprotection, and is a biomarker positively correlated with the prognosis of breast and prostate cancer." (PMID 36936373, 2023). "APOD is a direct transcriptional target of the AR, and a DHT-dependent secretion of APOD has been observed in prostate cancer cells." (PMID 27583472, 2016).
cervical cancer (8 papers, 2021 to 2025). A primary or metastatic malignant neoplasm involving the cervix. "In our study, APOD was lower-expressed in high-risk group as compared with low-risk group, suggesting that low-expressed APOD was associated with unfavorable prognosis of cervical cancer." (PMID 35184747, 2022). "Based on three genes of APOD, APOC1, and SQLE, the risk prediction model for the prognosis of patients with cervical cancer was established, tested and validated." (PMID 36536343, 2022). "In the study, APOD, APOC1 and SQLE were identified as prognostic genes, and a prognostic genes-based risk model was constructed and validated, which will provide a novel viewpoint and reference value for the treatment and prognosis of cervical cancer." (PMID 36536343, 2022). "APOD is down-regulated in cervical cancer compared with normal cervix." (PMID 33671013, 2021). "Simultaneously, the mRNA expression of APOD, APOC1, and SQLE was further assayed in cervical cancer tissues and normal tissues." (PMID 36536343, 2022). "For example, genes like APOD, ACKR1, and SFRP4 have been recognized as significant in cervical cancer, and our analysis supports their involvement in tumor progression and patient survival, thereby reinforcing their potential as biomarkers in clinical practice." (PMID 40678068, 2025). "After one-way and multivariate analysis of variance, we finally obtained three prognostic genes of APOD, APOC1 and SQLE significantly related to survival, and the expression of which was assayed in 10 cervical cancer tissue samples and 10 normal samples by RT-qPCR." (PMID 36536343, 2022).
colorectal cancer (8 papers, 2015 to 2025). A primary or metastatic malignant neoplasm that affects the colon or rectum. "A higher APOD expression level detected in breast and colorectal cancer tissues has been proven to be associated with a poor prognosis." (PMID 36422531, 2022). "In colorectal cancer, APOD was identified as a cancer stem cell-related gene." (PMID 40989158, 2025).
Insulin resistance (8 papers, 2017 to 2024). Increased resistance towards insulin, that is, diminished effectiveness of insulin in reducing blood glucose levels. "In abdominal adipose tissue, higher APOD protein levels are associated with lower BMI, waist circumference and less insulin resistance." (PMID 34638803, 2021). "Conversely, another study showed that mice overexpressing human ApoD developed hepatic steatosis and insulin resistance over time, with the accumulation of arachidonic acid and overactivation of PPARγ believed to contribute to the pathogenesis." (PMID 38375199, 2024). "In particular, it was observed that a target of JNK signaling, the lipocalin Neural Lazarillo (NLaz)—the ortholog of human apolipoprotein D (ApoD)—is strongly expressed in HSD flies; in contrast, animals heterozygous for an NLaz null mutation are fully protected from HSD-induced insulin resistance." (PMID 34681954, 2021). "In addition, we measured RNA levels for Neural Lazarillo (NLaz; homologue of the human Apolipoprotein D), which is a marker for insulin resistance in flies fed HSD34." (PMID 31221967, 2019).
coronary artery disease (7 papers, 2009 to 2025). "This explains why diseases associated with lipid impairment, such as coronary artery disorders (CADs), show an increase in ApoD levels in their HDLs, correlating with ApoD levels." (PMID 39767175, 2024). "Recent data indicate thataberrant apoD expression is associated with altered lipid metabolism and riskof coronary artery disease." (PMID 19946382, 2009). "However, one study showed that high circulating levels of apoD are associated with poor prognosis in coronary artery disease." (PMID 40485857, 2025). "Some studies have shown an increase in apoD in the HDL proteome of individuals with coronary artery disease and in areas of human atherosclerotic lesions as well as in apoE knockout mouse plasma." (PMID 32921312, 2020). "Moreover, ApoD was found to be enriched in high-density lipoproteins as well as blood plasma extracellular vesicles isolated from patients with coronary artery diseases." (PMID 35990326, 2022). "Altered expression of APOD was not reported to be significantly associated with coronary heart disease in our prior FHS investigation, but the cases were not of early onset and only half of the cases had prior MI." (PMID 33568140, 2021). "ApoD may be directly involved in regulation of SR-BI levels as SR-BI−/−: apoE−/− double knockout mice, a mouse model of coronary heart disease (CHD), had significantly higher apoD mRNA expression levels." (PMID 25548917, 2014).
multiple sclerosis (7 papers, 2018 to 2025). A progressive autoimmune disorder affecting the central nervous system resulting in demyelination. "In general terms, exosomes derived from both human and mice astrocytes are enriched in apolipoprotein D (ApoD), a molecule described for its beneficial properties against aging, AD, and multiple sclerosis." (PMID 35813501, 2022). "Apolipoprotein D (Apo D) overexpression is a general finding across neurodegenerative conditions so the role of this apolipoprotein in various neuropathologies such as multiple sclerosis (MS) has aroused a great interest in last years." (PMID 33514021, 2021).
Cognitive impairment (6 papers, 2019 to 2026). Abnormal cognition is characterized by deficits in thinking, reasoning, or remembering. "Elevated APOD levels in oligodendrocytes may also play a role in the cognitive impairments associated with HFD." (PMID 40692664, 2025). "APOD, Apolipoprotein D, has been widely studied in the context of neuroprotection and cognitive disorders, potentially exerting its effects via lipid transport mechanisms." (PMID 41601593, 2026). "There was a decreased level of ApoD in patients with mild cognitive impairment vs. control and a decreased level of ApoD in patients with AD vs. control." (PMID 39767175, 2024). "Although the involvement of ApoD as a biomarker of brain aging has been described in APOE ε4-related oxidative damage, cognitive impairment, and AD risk, to our knowledge, alcohol effects on ApoD have not been studied in abstinent AUD patients with cognitive impairment." (PMID 38535924, 2024). "This reinforces the idea that apolipoprotein D and E metabolism may reflect a cognitive disorder." (PMID 37108152, 2023). "Our results indicated higher plasma ApoD concentrations in AUD patients, similar to those of AD patients, and in AUD patients with cognitive impairment, similar to those of AD patients with cognitive impairment." (PMID 38535924, 2024).
metabolic syndrome (6 papers, 2009 to 2024). A cluster of metabolic risk factors for CARDIOVASCULAR DISEASES and TYPE 2 DIABETES MELLITUS. "Analysis of the proteomic profiles of 274 participants from the Qatar Biobank database showed reduced levels of HDL-related apolipoproteins (ApoM and ApoD) in patients with dyslipidemia and concomitant vitamin D deficiency." (PMID 39518736, 2024). "Adipose tissue releases large amounts of bioactive factors called adipokines, many of which are involved in inflammation, glucose homeostasis, and lipid metabolism, such as APOD which is positively associated with the metabolic syndrome." (PMID 37197688, 2023). "RBP4 and FABP4 are positively associated with metabolic syndrome, while APOD and LCN2 are ubiquitously expressed proteins with deleterious or beneficial effects, depending on their anatomical site of expression." (PMID 34638803, 2021). "Geneticvariants of apoD are associated with abnormal lipid metabolism andincreased risk of developing metabolic syndrome." (PMID 19946382, 2009). "Here, the possible correlation of a reduced form of expressed APOD in β-thalassemia bone marrow plasma, with relevant functions of APOD in lipid metabolism, could be related to the dyslipidemia and other complications in patients." (PMID 30813444, 2019). "Here we focus our review on recent advancestoward our understanding of apoD in lipid metabolism and address whetherapoD dysregulation contributes to the pathogenesis of dyslipidemia andatherosclerosis." (PMID 19946382, 2009).
myocardial infarction (6 papers, 2014 to 2025). Gross necrosis of the myocardium, as a result of interruption of the blood supply to the area, as in coronary thrombosis. "ApoD protects against ischemia-reperfusion injury in myocardial infarcts and has potent antioxidant activity, which may buffer the placenta once the maternal blood flow is established." (PMID 34100896, 2021).
astrocytoma (5 papers, 2017 to 2023). "In addition, APOD has been identified to be associated with astrocytoma progression." (PMID 33042807, 2020). "Recently, it was demonstrated that ApoD can be internalized in BSG-KO U87 astrocytoma cells, pointing towards another mechanism of entry for this lipocalin." (PMID 37237893, 2023). "Analysis of the subcellular distribution of BSG and ApoD in 1321N1 astrocytoma cells reveals that both proteins co-localize only on the cell surface." (PMID 35460054, 2022). "If ApoD targeting to lysosomes is regulated by oxidative stress, we wondered why there is a significant colocalization of ApoD with Lamp2 in 1321N1 astrocytoma cells under control conditions." (PMID 28182653, 2017). "Thus, the mechanism controlling lysosomal targeting of ApoD also occurs in the astrocytoma cell line 1321N1." (PMID 28182653, 2017). "ApoD protein was detected almost exclusively in the TX114-DRM (fraction 3), floating over the 35% sucrose layer, of membranes isolated from different sources: two human astrocytic cell lines (1321N1 astrocytoma and U87 glioblastoma), primary mouse astrocytes and mouse brain." (PMID 35460054, 2022).